CDK6 (cyclin dependent kinase 6)
Diseases named in the same sentence as CDK6 in open-access papers (continued):
Sharing a sentence is not in itself a finding about the gene and the disease.
cancer (continued). "Cancer cell lines derived from blood and lymphocytic malignancies, which have high expression of Cdk6, show a significant dependency on Fbxo7." (PMID 35670764, 2022). "The CDK6 complexes promoted cancer cells to enter the S phase, thereby enhancing cell proliferation and growth." (PMID 36140219, 2022). "In all cancers like colon, breast, lung, prostate, and stomach, the CDK6 expression level is very high, which signals cancerous cells to show resistance against the several drug molecules, chemotherapy and radiotherapy through continuous mutation." (PMID 35148332, 2022). "Some studies demonstrated that many tumorigenic events ultimately drove cancer cell proliferation by regulating CDK4 or CDK6 complexes in the G1 phase of cell cycle." (PMID 36408174, 2022). "Some members of CDK family including CDK1, CDK2, CDK4 and CDK6 have been reported to be involved in the regulation of cell cycle, thus participating the development and progression of cancer." (PMID 35517403, 2022). "In cancer cell lines, p21 acts as an activator to synthesize and activate cyclin D/Cdk4 or Cdk6 complexes to enhance proliferation efficiency." (PMID 36057545, 2022). "From the KEGG software was chosen the pathway in cancer, in which Bcl2 and CDK6 are target genes related to the activity of EDCs." (PMID 36498866, 2022). "CDK4 and CDK6 are targets for cancer therapies because they are part of the CCND–CDK4/6–CDKN2A–Rb pathway, which mediates the cell cycle transition from G0/1 to S phase." (PMID 36033522, 2022). "Palbociclib, ribociclib, and abemaciclib are highly selective and reversible inhibitors of CDK6 that interact with the ATP binding pocket of CDK6 and form hydrogen bonds and are used for the treatment of cancer." (PMID 35720007, 2022). "Knockout of the cdk6 gene unveiled a novel targeting pathway for overcoming ABCB1-mediated MDR in cancers." (PMID 35459184, 2022). "The CDK6 is a protein with significant importance at the cell-cycle level, and it is found in large amounts in certain types of cancer, like BC, resulting in a resistance to inhibitors." (PMID 36232374, 2022). "Since CDK6 is considered an attractive drug target for cancer therapy, we aimed to see the CDK6 inhibitory potential of Selonsertib." (PMID 35720007, 2022). "Cell cycle proteins that are often dysregulated in malignant cells, such as cyclin-dependent kinase (Cdk) 4 and Cdk6, have attracted considerable interest as potential targets for cancer therapy." (PMID 35725908, 2022). "The overexpression of CDK6 initiates the multidrug-resistant gene that favors the growth and development of cancer cells and protects the cells from apoptosis." (PMID 35720007, 2022). "We used western blotting to investigate the expression of several factors that are known to play significant roles in human cancers, including CDK6, Cyclin D1, PIK3CA, P-AKT, and P-mTOR." (PMID 34966665, 2021). "CDK6, as a critical member of cyclin-dependent kinases, it has been well known that the role of CDK6 in promoting cancer development from previous studies." (PMID 33976724, 2021). "The present study provided evidence that PI3K/Akt/NF-κB/mTOR/STAT3/CDK6 signaling network collectively contributes to generating cancer stemness in GBM." (PMID 34572040, 2021). "The transcription factor c-Myc plays an important role in the regulation of cell cycle through modulating cell cycle controllers, such as CDC25A, CDK4, CDK6, Rb, and p-Rb in cancer cells." (PMID 33572615, 2021). "In light of the critical role of the pathway cyclin D/CDK4 and CDK6/Rb in cell cycle progression, one can easily argue the relevance of its deregulation in cancer cells." (PMID 34445095, 2021). "Inhibitors of CDK6 are also being tested in clinical trials for several types of cancer, with promising results." (PMID 33542744, 2021). "Firstly, CDK2, CDK4, and CDK6, these three CDKs are often all elevated in clinical patient samples of many cancers." (PMID 33579185, 2021).
cancer (continued). "We also identified cyclin-dependent kinase-6 (CDK6) showing overexpression across cancer types, primarily overexpressed in MB (24%), HCC (23%), BRCA (17%), and PRAD (16%) cases (FDR ≤ 0.026)." (PMID 34552204, 2021). "In preclinical cancer models, continuous inhibition of CDK4 and CDK6 by abemaciclib led to cell cycle arrest and death of cancer cells." (PMID 33797023, 2021). "Only the CCND1-CDK4 and CDK6 complex has raised interest as a possible actionable target, whereas, in contrast, despite its prognostic relevance in cancer, the regulatory member CCND1 per se has received less attention." (PMID 34445095, 2021). "It has been reported that the abnormal levels of CDK4, CDK6, and cyclin D1 in various human cancer cells are closely related to the abnormal proliferation of cancer cells." (PMID 34574146, 2021). "The discovery of these roles of CDK4 and CDK6 in several cellular processes has certainly positively contributed to the further clinical development of CDK4/6i in different types of cancer, used alone or in combination with other therapeutic approaches." (PMID 34204543, 2021). "Overall, our results reveal a critical TAZ-CCND1-CDK4/CDK6 signaling axis, suggesting novel therapeutic approaches to eliminate both BCSCs and therapy-resistant cancer cells." (PMID 34211974, 2021). "More relevant to our model, proliferation can also be evoked by the presence of low concentrations of p21 protein (not a complete knock-out), through the assembly and activation of cyclin D/Cdk4 or Cdk6 complexes, as shown in cancer cell lines." (PMID 33925586, 2021). "Abnormal regulation of the CDK4- and CDK6-cyclin D-INK4-retinoblastoma protein (Rb) signaling pathway is one of the most common aberrations noted in many human cancers, in particular, in GBMs, which cells show excessive CDK4/CDK6 activation." (PMID 34440090, 2021). "CDK6 and CDK4, phosphorylate and thus regulate the activity of tumour suppressor Retinoblastoma protein, making CDK6 an important protein in cancer development." (PMID 34298667, 2021). "Protein expression by western blot indicated that APC shRNA1 cells have significantly increased CDK6, which has been frequently observed in different cancer types." (PMID 34370741, 2021). "Previous studies have shown that the up‐regulation of CDK6 activity is related to the occurrence of several cancers." (PMID 33586348, 2021). "CDK6 further facilitates cancer cell survival of FLT3-ITD+ AML by directly activating transcription of the proviral integration site for Moloney murine leukemia virus 1 (PIM1), another important leukemogenic driver." (PMID 32260549, 2020). "Ribociclib was the second selective CDK4/CDK6 inhibitor to gain the market approval as a cancer therapy in combination with an aromatase inhibitor." (PMID 32373584, 2020). "This has prompted the suggestion that the predominance of Cdk6–Cyclin D-p27 trimers depletes p27 from the pools of Cdk2 to elevate Cdk2 activities and confer palbociclib resistance in cancers in which Cdk6 expression is elevated." (PMID 33052073, 2020). "We further show that elevated CDK4 expression is a favorable prognostic index for cancer patients instead of high CDK6 expression that is close to poor prognosis." (PMID 33282875, 2020). "In HHC, NNT-AS1 can sponge miR-363, reducing the targeted inhibition of cyclin-dependent kinase 6 (CDK6) by miR-363, thereby increasing the expression of CDK6 and promoting proliferation of cancer cells." (PMID 33113895, 2020). "We found that CDK6 expression was significantly higher in the cancer tissues compared to the adjacent normal tissues." (PMID 32911343, 2020). "In fact, targeting cancer-related genes such as CDK6 and CDC43, miR-137s is involved not only in the regulation of transition from pluripotentency to differentiated states but also in apoptosis, suggesting that it is also associated with cancer." (PMID 32858868, 2020).
cancer (continued). "Palbociclib is a selective inhibitor of CDK4 and CDK6 and it was the first inhibitor of CDKs that was approved as a cancer therapy in combination with letrozole, an aromatase inhibitor." (PMID 32373584, 2020). "Cyclin-Dependent Kinase 6 (CDK6) plays an important role in cancer progression, and thus, it is considered as an attractive drug target in anticancer therapeutics." (PMID 32429317, 2020). "For instance, miR-218 can induce cell-cycle arrest at the G1 phase by targeting the 3ʹ-UTR region of CDK6/Cyclin D1, and overexpression of miR-24 increases the percentage of cells in G1 phase in HepG2 and K562 cancer cells." (PMID 32128112, 2020). "This study screens a series of plant-derived natural compounds against CDK6 to find a potent inhibitor of CDK6 that can be used as a drug lead in CDK6 directed cancers." (PMID 32429317, 2020). "These factors, produced by amniotic stem cells, can regulate the expression of cancer cell proteins associated with the cell cycle, such as cyclin-dependent kinases (CDK2, CDK4, CDK6) and cyclins (cyclin D2, cyclin E1, cyclin H)." (PMID 32972410, 2020). "Overall, the present study provides a different and novel insight into the possible targets of EA, particularly in cancer cells where the expression of CDK6 is high." (PMID 32429317, 2020). "We generated, for the first time, highly active VHL-based PROTACs with considerable CDK6 selectivity in a broad range of different human and murine cancer cells." (PMID 33133483, 2020). "The cdk4, cdk6, rb1, and e2f1 genes are expressed in a wide range of cancers according to analysis of the TCGA PANCAN database, which is composed of 12,839 samples." (PMID 32357912, 2020). "Cyclin-dependentkinase 6 (CDK6) was reported to be a vital regulator of cell cycle progression andcorrelated with various cancers including NSCLC." (PMID 33196759, 2020). "For example, experiments can be carefully designed to investigate the effect of CDK4/CDK6 inhibitors in treating Subtype_2 cancer patients using in vitro cancer cell line model, ex vivo or in vivo cancer models." (PMID 33344220, 2020). "CDK4/CDK6 inhibitors are among the most exciting new anti-cancer drugs of the past 10 years, and are approved by the FDA for patients with ER+HR− breast cancer." (PMID 32198354, 2020). "CDK6, an oncogene, promotes cell proliferation in many kinds of cancers and regulates cell migration." (PMID 30530570, 2019). "miR-1296-5p targets different genes and cancer pathways in different contexts; therefore, we identified two novel targets, CDK6 and EGFR, for miR-1296-5p to provide an understanding of the underlying mechanism." (PMID 30530570, 2019). "Recent studies have identified an additional role for CDK6 in the transcriptional regulation of cancer-relevant genes such as VEGF-A and EGR1 in hematopoietic malignancies." (PMID 30858922, 2019). "In this study, we demonstrated that an increased expression of phosphorylated NPM/B23 (at Thr199) in cancer cells promotes its interaction with CDK6 and plays a key role in endometrial tumorigenesis." (PMID 31330844, 2019). "Next, we checked the localization of cell cycle regulating proteins such as CHK1, CHK2, Cyclin D1, and CDK6 in Lanatoside C treated cancer cells and observed the presence of proteins in the extracellular matrix." (PMID 31783627, 2019). "We and others have shown that treatment of drug naïve cells with BET inhibitors results in the potent and rapid repression of a set of broadly expressed genes such as Myc, Bcl2 and Cdk6 that are essential for the survival of cancer cells 31–34." (PMID 31222014, 2019). "Mitotic signals stimulate CDK4 and CDK6 activities, which promote cancer cell proliferation through the entrance of G1 into the S phase in cell cycle." (PMID 31906234, 2019). "We identified 156 focal amplifications and 69 focal deletions, in well-known oncogenes, such as ERBB2, CCNE1, KRAS, MYC, EGFR, and CDK6, and cancer-related genes such as GATA4, GATA6, CD44 and ZNF217." (PMID 31570735, 2019).
cancer (continued). "As expected, the expression of CDK6 was significantly inhibited by ERK inhibitor in TRIM59 overexpressed cancer cells." (PMID 30515965, 2019). "The complex is also composed by an activating sub-unit, the cyclin D. This kinase has been shown to phosphorylate tumor suppressor protein, Rb, making CDK6 an important protein in cancer development." (PMID 30123094, 2018). "The cell cycle kinase CDK6 has been pursued as a genetically validated cancer drug target for a broad spectrum of cancers, including AML." (PMID 30544932, 2018). "Up-regulation of CDK6 has been shown to be related to the development of several types of human cancers, such as breast, colon, pancreatic, bladder and oral cancers." (PMID 29715320, 2018). "This compound is a CDK4/CDK6 inhibitor that efficiently induces senescence in responsive cancer cells." (PMID 30012580, 2018). "Flavonoids, a class of natural compounds with variable phenolic structures, have been found to possess anti-cancer activities by modulating different enzymes and receptors like CDK6." (PMID 29715320, 2018). "Although CDK6 is overexpressed at a very high frequency in cancer cells, it has a low detectable level in healthy cells." (PMID 29715320, 2018). "In contrast, CDK6 dependence was almost exclusively seen in cancer cell lines of hematopoietic or lymphoid origin, and these lines also often showed CCND3 dependence." (PMID 30443290, 2018). "It is known that components of the CDK4–cyclin and CDK6–cyclin complexes are frequently altered in cancer." (PMID 29464035, 2018). "Another important example of a kinase inhibitor is Palbociclib which is an oral, reversible, selective, small-molecule inhibitor of cyclin-dependent kinase (CDK) 4 and CDK6 for the treatment of cancer." (PMID 28439316, 2017). "IPA analysis of these unique up-regulated genes indicated that some genes were associated with cell transformation during cancer progression (ABL1, TRIO, FOSB, NRCAM, TRIB2 and CDK6) and others with cell survival (e.g., BCL10, BBC3, FGF8, HSPA4 and SOD1)." (PMID 29137349, 2017). "CyclinD-CDK4/CDK6 axis has an important role in the survival and proliferation of cancer cells, which mainly takes effect through regulating the cell cycle." (PMID 28415819, 2017). "We find that cancer-associated p16INK4a mutations differ in their modes of action toward CDK4 and CDK6 and in their abilities to displace CDK4 and CDK6 from Cdc37." (PMID 29091774, 2017). "Other oncogenes or cancer-associated genes such as CCNE1 (19q12; O15), CD44 (11p13; Y21), CDK6 (7q21.2; Y11), GATA4 (8p23.1-p22; O19), and GATA6 (18q11.2; O17) were also located in regions with high copy number gains." (PMID 29190909, 2017). "It has been reported that the cell cycle regulatory protein expression of cyclin A, cyclin E, cyclin D, Cdk4, Cdk6 and Cdk2 were inhibited by the activation of p21 in human cancer cells." (PMID 27007366, 2016). "Since several CDK4/CDK6 inhibitors have been also used in clinical trials in various types of cancers, it would be worth investigating the effectiveness of combinational therapies using BET bromodomain inhibitors as well as CDK6 inhibitors for SCLC patients." (PMID 27764802, 2016). "The frequency of CDK4/CDK6 deregulations observed in transformed cells suggests that many cancer cells are dependent on high CDK4/CDK6 activity." (PMID 27323399, 2016). "Experimental overexpression of miR-214 in HCC cells leads to suppression of E2F2, CDK3, and CDK6, cell-cycle arrest at the G1–S checkpoint, and disrupted proliferation of the cancer cells." (PMID 26498144, 2016). "As the regulatory subunits of CDK4 or CDK6, CCND1 and CCND2 are required for cell cycle G1/S transition, and thus have been implicated as proto-oncogenes and attractive targets for cancer therapy." (PMID 27494902, 2016).
cancer (continued). "Re-expression of miR-34a in cancer cell lines induced senescence and cell cycle arrest at least in part by targeting CDK6, indicating that miR-34a represents a tumor suppressor gene which is inactivated by CpG methylation in multiple types of cancer." (PMID 26580663, 2015). "The mechanism of the higher expression of EphB2 acting as a predictive factor for QYHJ treatment arose as a result of the upregulation of EphrinB1, which stimulated the EphB2-expressing cells to inhibit cancer cell growth by downregulating the CDK6 expression." (PMID 24959213, 2014). "CDK4 and CDK6 control the G1-S transition through the cell cycle and recent studies of genetically-engineered mice suggest that CDK4 or CDK6 is used to drive the cell cycle in each type of cancer." (PMID 24765199, 2014). "The results demonstrated that silencing EphB2 promoted cancer growth by stimulating cell proliferation through a mechanism of G1/S phase breakthrough, which was dependent on a cyclin D1/CDK6 cell cycle regulating signal." (PMID 24959213, 2014). "In SK-TRb cells, T3 down-regulated mRNA levels of Ccnd2, Cdk6, Cdc25, E2f3, c-Myb, Wee1 and Chk1 involved in cell proliferation and cancer." (PMID 24796297, 2014). "The cyclin D-CDK4 and cyclin-CDK6 complex drives the cell cycle through G1-S transition via phosphorylation of RB in various types of cancer." (PMID 24765199, 2014). "By contrast, CDK6 knockdown markedly reduced the expression of these phosphorylated RB proteins in the carcinoma cells." (PMID 24765199, 2014). "Western blotting revealed that CDK1, CDK2, CDK4 and CDK6 proteins were expressed at much higher levels in the carcinoma tissues than the matched normal tissues." (PMID 24765199, 2014). "PD is a highly selective, orally administered inhibitor of both CDK4 and CDK6 kinase activity and is currently being evaluated in clinical trials for a variety of adult cancers." (PMID 24098593, 2013). "In vivo, a significant negative correlation is also observed between the GAS5 levels and the CDK6 levels in cancer tissues (r2 = 0.168, p = 0.013)." (PMID 24069260, 2013). "In cancer it has been shown that many miRs, such as miR-107, miR-129, and miR-449a/b, target and down-regulate CDK6 to reduce cell proliferation and invasion." (PMID 23950948, 2013). "Eight proliferation-associated genes including CCND1, CDK1, CDK6 and 26 apoptosis-regulating genes (e.g. SOCS3) were differently expressed between juvenile and cancer groups mostly supporting the pronounced cell growth in CRC." (PMID 24098334, 2013). "CDK6 is a direct target of miR129 in CC, so downregulation of miR-129 results in upregulation of CDK6 and cell cycle deregulation in this carcinoma." (PMID 24490161, 2013). "The transcription levels of the two H3K27 demethylase genes, UTX and JMJD3, the H3K27 methyltransferase EZH2 and the CDK4/CDK6 inhibitor p16INK4a were determined by qRT-PCR in cancer tissues and adjacent normal tissues from 36 RCC patients." (PMID 23057811, 2012). "The paradigm relating cell cycle control, cyclin-dependent kinases and cancer has changed from our classical understanding, however, with reappraisal of the mandatory requirement of Cdk2, Cdk4 or Cdk6 for normal cell division." (PMID 21668989, 2011). "We observed that after treating cells for 48 h with the SCD1 inhibitor, cancer cells exhibited a marked decrease in the content of both cyclin D1 and CDK6." (PMID 20613975, 2010). "We also have found that miR-29a can potentially target BCL2L2, VEGFA and CDK6, which are involved in cancer initiation and progression." (PMID 20668671, 2010).